LINC01010 (long independently transcribed non-coding RNA 1010)
Gene: Long non-coding RNA gene on chromosome 6 (134,343,271 to 134,504,581, forward strand). Ensembl gene ENSG00000236700.
Diseases named in the same sentence as LINC01010 in open-access papers:
LINC01010 is named in the same sentence as 6 diseases in open-access papers, as found by Europe PMC text mining. Sharing a sentence is not in itself a finding about the gene and the disease. The quoted sentences say what the papers report.
lung carcinoma (3 papers, 2020 to 2022). "LINC01010 has a significant prognostic value that suppresses cancer cell migration and invasion of lung cancer." (PMID 33727952, 2021). "Result revealed a 6 lncRNA signal, including LINC01287, SNAP25-AS1, LINC00470, AC104809.2, LINC00645 and LINC01010, as an independent prognostic factor for predicting OS in lung cancer patients." (PMID 32518519, 2020). "Inhibition of LINC01010 may promote the migration and invasion of lung cancer cells and help in the prediction of neuroblastoma prognosis." (PMID 35721492, 2022). "To further determine whether LINC01010 affects lung cancer cell migration ability, we knocked down its expression by transfecting siRNA for LINC01010 into A549 or SPC-A-1 cells." (PMID 32518519, 2020). "Furthermore, we found that suppression of LINC01010 promoted lung cancer cell migration and invasion." (PMID 32518519, 2020). "Finally, we used Transwell assays with lung cancer cell lines to verify that LINC01010 acts as a tumor suppressor." (PMID 32518519, 2020). "However, either in A549 cells or SPC-A-1 cells, transfection of LINC01010 siRNA had little effect on the proliferation of lung cancer cells." (PMID 32518519, 2020). "Furthermore, we noted that expression of LINC01010 was positively correlated with OS and negatively correlated with metastasis and lung cancer stage." (PMID 32518519, 2020). "Therefore, LINC01010 may play an important role in tumorigenesis in lung cancer by competing with miR-372." (PMID 32518519, 2020). "Therefore, we postulate that LINC01010 may play a more crucial role in the pathogenesis and prognosis of lung cancer." (PMID 32518519, 2020). "In sum, LINC01010 inhibits the migratory and invasive capacity of lung cancer cells, but not proliferation." (PMID 32518519, 2020).
neuroblastoma (3 papers, 2021 to 2022). Neuroblastoma (NB) is the most common solid, extracranial childhood tumor. "Higher LINC01010 expression was significantly related to better survival, suggesting that LINC01010 is a potentially potent prognostic target in neuroblastoma." (PMID 35592755, 2022). "For example, LINC01010 is positively correlated with the survival of neuroblastoma (NBL) patients and is a potential biomarker of NBL." (PMID 34830378, 2021).
breast carcinoma (1 paper, 2021). "Furthermore, LINC01010 and C6orf99 exhibited meaningful properties in basal-like cell subtypes, and their high expressions better predicted the more aggressive form of breast cancer, such as basal-like BRCA." (PMID 33727952, 2021).
hepatocellular carcinoma (1 paper, 2023). A malignant tumor that arises from hepatocytes. "LINC01010 is downregulated in HBV-transgenic hepatocellular carcinoma cell line and is a potential tumor suppressor that inhibits the development of HBV-associated hepatocellular carcinoma." (PMID 36819091, 2023).
cancer (4 papers, 2020 to 2022). A tumor composed of atypical neoplastic, often pleomorphic cells that invade other tissues. "It has been reported that LINC01010 is a novel biomarker for the diagnosis and prognosis for cancer." (PMID 34830378, 2021). "The findings indicated that there were 19 common DMlncs in more than 15 cancers (RP4-792G4, RP5-855F14, OTX2-AS1, RP11-52L5, CYP1B1-AS1, RP11-175E9, RP11-552E20, HCCAT3, RP11-718O11, HOXA-AS2, RP3-326L13, AC007228, RP11-297B11, CTC-523E23, LINC01010, RP11-227D2, EVX1-AS, AC018730, and RP11-465L10)." (PMID 35721492, 2022).
tumor (3 papers, 2020 to 2023). "The expression level of LINC01010 was lower in tumor tissues than in normal tissues in the TCGA-LIHC cohort." (PMID 34830378, 2021). "Taken together, LINC01010 is a potential tumor suppressor that may restrain HBV-related HCC development." (PMID 34830378, 2021). "The LINC01010 can inhibit the proliferation and migration of HCC cells by interacting with vimentin, suggesting that LINC01010 may function as a tumor suppressor and a potential target for treatment." (PMID 34830378, 2021). "Our data demonstrate that LINC01010 may function as a tumor suppressor in HCC." (PMID 34830378, 2021). "We further investigated whether LINC01010 was related to epithelial–mesenchymal transition (EMT) markers, which can be used to indicate an increased capacity for migration of tumor cells." (PMID 32518519, 2020).